CRP (C-reactive protein)
Diseases named in the same sentence as CRP in open-access papers (continued):
Sharing a sentence is not in itself a finding about the gene and the disease.
lung cancer (continued). "In multivariate analysis, mortality-related factors were male sex, advanced age, more than two comorbidities, C-reactive protein >20 ng/mL, primary brain tumors and lung cancer." (PMID 34638235, 2021). "We set out to test if postoperative CRP levels, leukocyte counts and fever in patients who underwent curative lung cancer surgery correlate with preoperative CRP values." (PMID 33080990, 2020). "The elevation of CRP-SAA was associated with lower survival rates for lung cancer patients, which made it a better prognostic marker than SAA or CRP, especially in early-stage patients." (PMID 33364190, 2020). "In lung cancer, CRP displayed more than 2-fold higher than normal value and increased approximately 80% risk of early mortality." (PMID 33344503, 2020). "A lung cancer diagnostic panel consisting of APOA1, CO4A, CRP, GSTP1, and SAMP expression levels reached 95% sensitivity and 81% specificity." (PMID 31976313, 2020). "In our previous study, proteomic analysis specifically identified the complex of CRP-SAA from serum samples of lung cancer patients with a significant difference from the normal candidates." (PMID 33364190, 2020). "In this study, we investigate if high preoperative CRP levels correlate with postoperative hallmarks of inflammation in patients undergoing pulmonary resection for the treatment of lung cancer." (PMID 33080990, 2020). "Two patients with lung cancer or multiple fractures due to a traffic accident showed a CRP level higher than 10 μmol/L." (PMID 33133795, 2020). "Previously, we identified the complex of CRP and SAA (CRP-SAA) with diagnostic and prognostic value better than either one of them in the serum of lung cancer patients." (PMID 33364190, 2020). "In the lung cancer patients, an elevated CRP level (25.96 mg/L vs 16.84 mg/L, P = .016) was observed for patients with DM." (PMID 32813914, 2020). "In lung cancer, inflammatory markers such as C-reactive protein (CRP), neutrophil-to-lymphocyte ratio, Glasgow prognostic score, and platelet-to-lymphocyte ratio (PLR) have been evaluated." (PMID 30886226, 2019). "This study intended to investigate the effects of serum high-sensitivity C-reactive protein (hs-CRP) on the incidence of lung cancer in male patients with pulmonary tuberculosis." (PMID 31497547, 2019). "Previous studies have revealed that a significant positive associations of S/L ratio with systemic inflammatory markers such as WBC, neutrophil and CRP were present in patients diagnosed with lung cancer and cholangiocarcinoma." (PMID 30718566, 2019). "It is also worth noting that an acute-phase protein response, defined as a C-reactive protein ≥10 mg L−1 was observed in 82% (35/43) of the sample with lung cancer prior to chemotherapy." (PMID 31450784, 2019). "Since IL-1β has been linked to airway inflammation, it will be of interest to know if the high CRP levels in the CANTOS trial at baseline were associated with an incidence of COPD, known to increase lung cancer risk." (PMID 30832375, 2019). "Of note, exploratory data from a large randomized trial has provided evidence that in subjects with high CRP, yet otherwise healthy, inhibition of IL-1β by canakinumab, reduced the incidence of lung cancer, as well as the lung cancer related mortality." (PMID 30365491, 2018). "We found that platelet, PCT, NLR and PLR, albumin, HDL, and CRP levels aided in lung cancer diagnosis and the detection of late-stage disease." (PMID 29941786, 2018). "Patients with lung cancer were approximately four times more likely to have a CRP level above the median (4.05 mg/L) than patients with other cancers (OR 4.49, 95% CI 2.74–7.35)." (PMID 28286467, 2017). "The mean log transformed values for ln (CRP) were higher in the patients with lung cancer than in the patients with other cancers in the unadjusted analysis (2.40 vs 1.24)." (PMID 28286467, 2017). "Both SAA and CRP also possess some prognostic potential for predicting survival of lung cancer patients." (PMID 28121629, 2017).
lung cancer (continued). "Patients with lung cancer were more likely to have a CRP level above the median (4.05 mg/L) than patients with other cancers (adjusted odds ratio = 2.67)." (PMID 28286467, 2017). "In the fully adjusted model, “lung cancer” had a 2.19-fold greater effect on ln (CRP) than “heart disease” and the same effect as an increase in FEV1 loss of 47% of the predicted value." (PMID 28286467, 2017). "In the fully adjusted model, the values for ln (CRP) were still higher in the patients with lung cancer than in patients with other cancers (2.09 vs 1.51)." (PMID 28286467, 2017). "In patients with lung cancer, we were unable to find a relationship between IL-22 levels, systemic leukocyte, lymphocyte or neutrophil counts and CRP (p = 0.19, 0.33, 0.28 and 0.35, respectively)." (PMID 27388918, 2016). "Our model incorporated several unique predictors of lung cancer risk, including MMEF as an index of airway obstruction, and the serum markers CEA, bilirubin, AFP, and CRP." (PMID 27805040, 2016). "An elevated level of serum C-reactive protein (CRP) is an indicator of poor prognosis in several cancer types, including lung cancer." (PMID 27695079, 2016). "An increase in CRP level in lung cancer patients compared to healthy individuals has been described." (PMID 26678281, 2016). "A noteworthy finding of the present study is the dissociation between local IL-22 concentrations and systemic parameters of inflammation such as CRP and leukocyte counts in patients with lung cancer." (PMID 27388918, 2016). "CRP-bound components obtained from the serum samples from lung cancer patients or healthy controls were analyzed by differential proteomics analysis." (PMID 26264146, 2015). "We also evaluated the value of this CRP complex as a potential prognostic marker in two independent cohorts of lung cancer patients." (PMID 26264146, 2015). "Systemic inflammation as measured by the biomarkers; C-reactive protein (CRP), leukocytes and fibrinogen is associated with a two to four-fold increased risk of comorbidities including cardiovascular disease and lung cancer." (PMID 26220864, 2015). "Elevated levels of serum C-reactive protein (CRP) have been reported to have prognostic significance in lung cancer patients." (PMID 26264146, 2015). "In conclusion, the present study reveals that serum CRP-SAA isolated from serum CRP-bound complexes is a potential marker for poor prognosis in lung cancer patients." (PMID 26264146, 2015). "For further confirmation, serum CRP-bound components from healthy controls or lung cancer patients were evaluated using 2-DE." (PMID 26264146, 2015). "Similar to total SAA, the serum levels of CRP-SAA in patients with lung cancer were elevated significantly compared with those in healthy controls (P < 0.001)." (PMID 26264146, 2015). "SAA was exclusively presented in the form of CRP-bound complexes in the serum of lung cancer patients." (PMID 26264146, 2015). "This study aimed to further identify CRP-bound components as prognostic markers for lung cancer and validate their prognostic value." (PMID 26264146, 2015). "Our results firstly suggest that polymorphisms in CRP and GPC5 genes have an association with susceptibility risk of lung cancer in the Chinese Han population." (PMID 25999661, 2015). "Our data agree with the results of previous studies in which increased SAA and CRP levels were found to be useful biomarkers for the prediction of lung cancer prognosis." (PMID 26264146, 2015). "ROC analysis showed that the area under the ROC curve (AUC) for CRP-SAA in the diagnosis of lung cancer was 0.903, which was higher than the AUC of 0.845 obtained for total SAA." (PMID 26264146, 2015). "Through a differential proteomic analysis, we found that several proteins were significantly up-regulated in the form of CRP-bound complexes in the serum of lung cancer patients." (PMID 26264146, 2015).
lung cancer (continued). "We selected seven genes (CRP, GPC5, ACTA2, AGPHD1, SEC14L5, RBMS3, and GKN1) that previously reported link to lung cancer (LC) and genotyped single nucleotide polymorphisms (SNPs) of these genes in a case-control study." (PMID 25999661, 2015). "CRP-SAA was identified specifically in serum samples from lung cancer patients by proteomic analysis." (PMID 26264146, 2015). "CRP-bound components in serum samples obtained from healthy controls or lung cancer patients were purified using anti-CRP carboxyl-coated polyethylene beads and subjected to SDS-PAGE." (PMID 26264146, 2015). "The 10 studies on CRP (7 cohort studies and 3 nested case-control studies) were published between 2005 and 2011 and involved a total of 1918 lung cancer cases." (PMID 22912790, 2012). "Sensitivity and specificity of CRP for predicting lung cancer was both 61% when using a cut-point of 2.1 mg l−1, whereas corresponding values for YKL-40 in risk prediction of gastrointestinal cancer were 63% using a cut-point of 69.0 μg l−1." (PMID 22095223, 2012). "The cumulative incidence of lung cancer as a function of age increased with increasing levels of CRP and YKL-40 (log-rank, P<0.001)." (PMID 22095223, 2012). "The multifactorially adjusted HR of lung cancer for a doubling of CRP levels was 1.35 (95% CI: 1.17–1.56), while further adjustment for YKL-40 levels resulted in a similar HR of 1.35 (1.16–1.57) (likelihood ratio test between models, P=0.99)." (PMID 22095223, 2012). "By maximising both sensitivity and specificity for prediction of lung cancer, a cut-point of 2.1 mg l−1 was identified for levels of CRP (sensitivity and specificity both 61%) and of 68.6 μg l−1 for levels of YKL-40 (sensitivity and specificity both 62%)." (PMID 22095223, 2012). "Hazard ratio of lung cancer for a doubling of CRP levels was 1.35 (1.17–1.56) and indifferent to adjustment for YKL-40 levels." (PMID 22095223, 2012). "The pooled RR of lung cancer for one unit change in natural logarithm (ln) CRP was 1.28 (95% CI 1.17–1.41)." (PMID 22912790, 2012). "A similar issue can be pointed out in the association of CRP and YKL-40 with lung cancer that the present results merely imply that CRP alone is enough to predict lung cancer risk." (PMID 22095223, 2012). "Epidemiologic findings are inconsistent concerning the associations between C-reactive protein (CRP), interleukin 6 (IL-6) and lung cancer risk." (PMID 22912790, 2012). "The area under the receiver operating characteristic (ROC) curve was 0.68 for the ability of YKL-40 to predict gastrointestinal cancer and 0.67 for the ability of CRP to predict lung cancer." (PMID 22095223, 2012). "Four proteins were found to be more abundant in the lung cancer samples than those of the controls, namely CRP (13.3 fold), SAA (2.0 fold), AAT (1.4 fold) and MUC1 (1.4 fold)." (PMID 16117833, 2005). "All of the sera from patients with lung cancer showed much higher levels of CRP and SAA compared to the sera from healthy controls." (PMID 16117833, 2005). "Proteins that exhibited higher abundances in the lung cancer samples relative to the control samples included C-reactive protein (CRP; a 13.3 fold increase), serum amyloid A (SAA; a 2.0 fold increase), mucin 1 and α-1-antitrypsin (1.4 fold increases)." (PMID 16117833, 2005). "More recently, it has been reported that cytochrome P450 3A activity, the principal drug metabolising enzyme in a variety of chemotherapeutic agents, is compromised in advanced lung cancer patients with an elevated C-reactive protein concentration." (PMID 15150622, 2004). "In a two-center study of lung cancer surgery patients, investigators found that CRP (and IL-6) levels rose in all patients postoperatively, including those who never developed any infection, meaning the markers’ additional predictive value was limited in the very early period." (PMID 41153812, 2025).
lung cancer (continued). "Based on this knowledge, it can be concluded that patients with lung cancer and comorbidities are more prone to infection, and low CRP levels in these patients may act as warning signs of infection." (PMID 40125102, 2025). "CRP cutoff values were determined with the aim of predicting an infection that might delay a chemotherapy cycle in patients with lung cancer undergoing chemotherapy." (PMID 40125102, 2025). "Of note, at the time of discontinuation due to disease progression, males exhibited significantly higher levels of CRP compared to females, suggesting a possible significant sex-related predictive impact on survival outcomes in lung cancer patients treated with ICIs." (PMID 39590174, 2024). "However, a significant increase in monocytes, neutrophils, and CRP was noted in patients with lung cancer." (PMID 39124797, 2024). "The levels of inflammatory factors such as IL-1β, IL-6, TNF-α, and CRP in the serum of the lung cancer mice increased, promoting the activation of inflammatory cells and stimulating the release of inflammatory mediators, leading to an increased risk of systemic inflammatory response." (PMID 39594117, 2024). "Higher CRP levels in patients with lung cancer than in healthy individuals have also been reported." (PMID 38750432, 2024). "The inflammatory microenvironment also promotes the progression and metastasis of lung cancer, and TNF-α CRP and IL-6 are common inflammatory factors, and their serum levels are generally elevated in lung cancer patients and are significantly correlated with tumor activity." (PMID 38957318, 2024). "We found that lung cancer CRA is primarily related to the patient's past surgeries, chemotherapy, KPS score, serum iron, CRP, albumin, and total cholesterol levels through the univariate analysis of clinical data and laboratory indices of 1040 lung cancer patients with CRA." (PMID 38562035, 2024). "We also discovered that CRP is a risk factor for the development of CRA in lung cancer patients with normal serum iron, but it is not a contributing factor for the reduction of CRA in patients with decreased serum iron levels." (PMID 38562035, 2024). "Elevated baseline CRP levels increased lung cancer risk in individuals with lower educational levels but not in those with higher educational levels." (PMID 39687887, 2024). "CRP is a risk factor for CRA in lung cancer patients with normal serum iron but not in patients with decreased serum iron." (PMID 38562035, 2024). "In addition, C-reactive protein (CRP), a clinical marker of inflammation associated with increased lung cancer risk and progression, has been shown to have an interesting relationship with ICIs." (PMID 37511306, 2023). "A detailed analysis of survival time for the three main diagnoses (lung, colorectal, and pancreatic cancer) showed that in patients with lung cancer, the covariates “CRP value,” “days from first diagnosis to randomization,” and “gender” were significantly associated with survival time." (PMID 36937336, 2023). "Moreover, CRP and WBC have been used as markers of the risk of incident lung cancer, and as predictors of early mortality or survival." (PMID 38288337, 2023). "While this finding is concordant with research on IL-6 and CRP in lung cancer patients undergoing chemotherapy and in prostate cancer patients treated with androgen deprivation therapy, it is in contrast to research examining cytokines and fatigue in other cancer patient populations." (PMID 37444517, 2023). "Based on our results, we identified CRP as a valuable HFD-induced modulator that can facilitate lung cancer progression, and suggest that it could serve as a potential target for lung cancer monitoring and therapy." (PMID 37929799, 2023).
lung cancer (continued). "Comparing the high C3 group to the low C3 group in lung cancer patients, we found that the levels of serum CRP (82.37 (61.89, 90.91) vs. 51.90 (43.19, 60.21), p < 0.05) and IL-6 (89.80 (66.57, 127.13) vs. 53.69 (31.61, 57.68), p < 0.05) were significantly higher in the high C3 patients." (PMID 36769748, 2023). "Our results suggest that respiratory failure may develop earlier in patients with lung cancer, especially in those with high CRP levels or a history of ICI administration." (PMID 36316726, 2022). "Serum levels of C-reactive protein (CRP), serum amyloid A (SAA), soluble tumor necrosis factor receptor 2 (sTNFRII), and monokines induced by gamma interferon (CXCL9/MIG) are associated with a prospective risk of lung cancer." (PMID 35769715, 2022). "Recent studies have shown that CRP levels during or after surgery could reflect the stress response of patients undergoing lung cancer surgery." (PMID 36033577, 2022). "CAR, as a combination of the two indexes plasma CRP and albumin, may be used as a simple biomarker to predict the survival status of patients with lung cancer." (PMID 36684183, 2022). "In addition to reduced CRP and IL-6 levels, cardiovascular events and death, canakinumab treatment lowered lung cancer incidence and mortality as well as total cancer mortality vs. placebo." (PMID 35406394, 2022). "Interestingly, in the Canakinumab trial, participants who had higher levels of CRP were the ones who appeared to benefit from Canakinumab treatment in reducing lung cancer incidence and mortality." (PMID 36532545, 2022). "Univariate analyses of the two groups revealed that long OS or SPP were associated with prognostic factors such as c-reactive protein (CRP) and advanced lung cancer inflammation index (ALI), indicating better clinical characteristics of patients continuing immunotherapy." (PMID 35582303, 2021). "The ongoing oxidative and inflammatory disturbances in our cohort may also be demonstrated by the generally lower concentrations of albumin and higher CRP and ceruloplasmin concentrations in lung cancer patients compared to the control group." (PMID 34832849, 2021). "High CRP values (>1 mg/dl) tended to be more frequent in stage IV lung cancer patients (p = 0.066)." (PMID 34077485, 2021). "In support, elevated serum levels of C-reactive protein (CRP) and high erythrocyte sedimentation rate (ESR) are both associated to lifestyle (i.e. smoking, air pollutant exposure) and are related to increased risk of lung cancer." (PMID 33187551, 2020). "Here, we retrospectively investigated if preoperative CRP levels correlate with postoperative CRP, leukocyte counts and fever in the context of anatomical lung resection and systematic lymph node dissection as first line lung cancer therapy." (PMID 33080990, 2020). "In our previous study, proteomics analysis specifically identified CRP-SAA complexes from serum samples of lung cancer patients, which could be used as diagnostic and independent prognostic markers for early-stage lung cancer patients." (PMID 33364190, 2020). "Indeed, several studies have confirmed that high levels of C-reactive protein, IL-6, IFN-γ, and IL-1β were positively associated with lung cancer risk." (PMID 32802852, 2020). "CRP seems to have at least a dual function in the context of lung cancer surgery." (PMID 33080990, 2020). "In conclusion, the preceding may be the mechanisms of the association between elevation of CRP-SAA and lung cancer poor prognosis." (PMID 33364190, 2020). "Importantly, these investigators found that reducing the inflammatory markers, CRP and IL-6 (and likely other pro-inflammatory proteins) with canakinumab (a monoclonal antibody against IL-1β) dramatically reduced the incidence of lung cancer in these patients." (PMID 33173057, 2020).